TIPE2 (TNF alpha induced protein 8 like 2)
Diseases named in the same sentence as TIPE2 in open-access papers (continued):
Sharing a sentence is not in itself a finding about the gene and the disease.
bladder urothelial cancer (2 papers, 2022 to 2025). "In multivariate Cox proportional hazard regression analysis, TIPE2 was a protective factor for progression-free survival in bladder urothelial carcinoma (p = 0.031), pT stage (p = 0.016) was a risk factor for progression-free survival, and age was a risk factor for overall survival (p = 0.020)." (PMID 35388275, 2022). "Using immunohistochemistry, 60 specimens of bladder urothelial cancer (UC) for the expression of TIPE2 and CD36 were studied and compared with the clinicopathologic parameters and survival data." (PMID 40060230, 2025). "The results clearly showed that TIPE2 was expressed in urothelial carcinoma of bladder (105 of 110 cases were positive)." (PMID 35388275, 2022). "In the present study, we demonstrated for the first time that TIPE2 was expressed in various degrees in bladder urothelial carcinoma tissues by IHC staining method." (PMID 35388275, 2022). "This study systematically analyzed the expression characteristics, clinicopathological features and prognosis of TIPE2 in bladder urothelial carcinoma." (PMID 35388275, 2022). "However, the expression condition and role of TIPE2 in the development and progression of bladder urothelial carcinoma are largely unknown." (PMID 35388275, 2022).
cervical cancer (2 papers, 2019). A primary or metastatic malignant neoplasm involving the cervix. "However, the clinical diagnostic and prognostic value of TIPE2 for cervical cancer is still unclear." (PMID 33817189, 2019). "In a recent study about intergrinαVβ6, TIPE2 expression was found to be lower in cervical cancer tissues and cervical benign lesions than in healthy cervical tissues." (PMID 33817189, 2019). "The results suggested that TIPE2 can suppress malignant phenotypes of cervical cancer cells in vitro." (PMID 33817189, 2019). "Another research reported that TIPE2 expression was reduced in cervical cancer tissues and cervical benign lesions." (PMID 33817189, 2019). "Our study also explored the molecular mechanism of TIPE2 in cervical cancer." (PMID 33817189, 2019). "The effect of TIPE2 on development of cervical cancer is largely unclear." (PMID 33817189, 2019). "In addition to cervical cancer, TIPE2 also plays a tumor suppressor role in most current studies on cancers." (PMID 33817189, 2019). "TIPE2 expression was higher in cervical cancer tissues than that in normal tissue." (PMID 33817189, 2019). "The effect of TIPE2 on cell metastasis of cervical cancer was further investigated in vitro." (PMID 33817189, 2019). "Research on the molecular mechanism of TIPE2 in cervical cancer is just beginning." (PMID 33817189, 2019). "Over expression of TIPE2 effectively inhibited the proliferation of cervical cancer cells." (PMID 33817189, 2019). "Moreover, TIPE2 can sensitize osteosarcoma cells to cis-platin by downregulating MDR1 transcription, while TIPE1 promotes cervical cancer progression." (PMID 31179241, 2019).
chronic hepatitis (2 papers, 2017 to 2021). An active inflammatory process affecting the liver for more than six months. "In chronic hepatitis infection, hepatitis B and C viruses attenuate the expression of TIPE2 and promote the occurrence of chronic hepatitis." (PMID 33815396, 2021). "A study by Li Kong showed decreased TIPE2 expression and enhanced TLR signaling in patients with HCV-mediated chronic hepatitis." (PMID 28626770, 2017).
fibrosis (2 papers, 2017 to 2022). the formation of excess fibrous connective tissue in an organ or tissue in a reparative or reactive process. "Furthermore, we also found that the relative mean integrated optical densities for hepatic TIPE2 protein in inflammation G3/4 and fibrosis S3/4 were significantly higher compared to that of the inflammation G1/2 and fibrosis S1/2 (P < 0.05)." (PMID 28390195, 2017).
gastric tumor (2 papers, 2018 to 2021). "To explore the role of TIPE2 in gracillin suppression of gastric tumors, we synthesized three fragments of TIPE2 siRNA sequence, which were respectively siTIPE2-1, siTIPE2-2, and siTIPE2-3." (PMID 34630074, 2021). "Therefore, we choose siTIPE2-2 as a tool for suppressing TIPE2 expression to illustrate the role of TIPE2 in gracillin suppression of gastric tumors." (PMID 34630074, 2021). "To further confirm whether gracillin inhibited gastric tumor cell proliferation via TIPE2, we conducted western blot assay to detect the AKT phosphorylation in the supplement of gracillin and siTIPE2 RNA in BGC823 cells." (PMID 34630074, 2021). "TIPE2 expression at mRNA level was significantly lower in gastric tumor lesions than in adjacent non-cancerous tissues (P < 0.05)." (PMID 30157801, 2018).
liver diseases (2 papers, 2017 to 2019). "In this study, we determined the dynamic expression of TIPE2 mRNA in PBMCs in different stages of HBV-associated liver diseases and identified the potential diagnostic value of TIPE2 mRNA as a biomarker for discriminating HBV-associated HCC from CHB and LC patients." (PMID 31661000, 2019). "However, the potential roles of TIPE2 mRNA at different stages of HBV-associated liver diseases have not yet been reported." (PMID 31661000, 2019).
liver fibrosis (2 papers, 2018 to 2019). "Functional analysis showed that TIPE2 might have protective effects on liver fibrosis by reversing the activated hepatic stellate cells." (PMID 31661000, 2019). "TIPE2 diminished liver fibrosis through reversal of activated hepatic stellate cells." (PMID 30274259, 2018). "TIPE2 possesses a protective effect on liver fibrosis and hence may serve as a potent target against this disease." (PMID 30274259, 2018). "Thus, owing to its protective effect, TIPE2 displays potential as an effective target against liver fibrosis." (PMID 30274259, 2018).
myasthenia gravis (2 papers, 2017 to 2018). Myasthenia gravis (MG) is a rare, clinically heterogeneous, autoimmune disorder of the neuromuscular junction characterized by fatigable weakness of voluntary muscles. "TIPE2 and TIPE1 have been found to exert their effect in Myasthenia Gravis and Parkinson’s disease, respectively, and thus can serve as important targets for therapies against these diseases." (PMID 30274259, 2018).
osteoarthritis (2 papers, 2020 to 2025). A noninflammatory degenerative joint disease occurring chiefly in older persons, characterized by degeneration of the articular cartilage, hypertrophy of bone at the margins and changes in the synovial membrane. "TNFAI8 and TIPE2‐deficient mice have been generated, and may prove useful in studying inflammatory processes such as back pain and osteoarthritis in the musculoskeletal field." (PMID 32613168, 2020). "Pending these investigations, further preclinical and clinical studies will be necessary to evaluate whether TIPE2 can be considered a potential senomorphic for osteoarthritis treatment." (PMID 40759632, 2025). "Collectively, these findings suggest that inducible activation of TIPE2 can reduce or inhibit TNF-α secretion, suppress SASP and inflammation, and ultimately alleviate cellular senescence and osteoarthritis." (PMID 40759632, 2025).
pancreatic cancer (2 papers, 2021 to 2023). "Taken together, our present study demonstrated that the expression of TIPE2 was reduced in human pancreatic cancer, which was negatively correlated with tumor size." (PMID 34249724, 2021). "Overexpression of TIPE2 significantly decreased cell proliferation, metastasis and increased apoptotic events in pancreatic cancer cell lines." (PMID 34249724, 2021). "In this study, we found the expression of TIPE2 was decreased in pancreatic cancer tissues compare to paracancerous tissues, which was negatively correlated with tumor size in patients." (PMID 34249724, 2021). "Meanwhile, overexpression of TIPE2 suppressed the migration and invasion of pancreatic cancer cells via decreasing the expression of MMPs and N-cadherin." (PMID 34249724, 2021). "To further evaluate the regulation role of TIPE2 in the malignancy of pancreatic cancer, we constructed pancreatic cancer cell lines overexpressing TIPE2 or vector control." (PMID 34249724, 2021). "To explore the immune-regulation role of TIPE2 in pancreatic cancer, we established the subcutaneous tumor model through injecting mouse Panc02/vector and Panc02/TIPE2 cells into mice." (PMID 34249724, 2021). "In our current study, the expression of TIPE2 was significantly decreased in pancreatic cancer compared to paracancerous tissues, that is consistent with other types of cancers." (PMID 34249724, 2021). "Overexpression of TIPE2 significantly suppressed the proliferation, metastasis, and promoted apoptosis of pancreatic cancer possibly through inhibition of PI3K/AKT and Raf/MEK/ERK signaling pathways triggered by TGFβ1." (PMID 34249724, 2021). "To investigate the function of TIPE2 in the migration and invasion of pancreatic cancer cells in vitro, we performed transwell assays using the highly metastatic pancreatic cancer cell line AsPC-1." (PMID 34249724, 2021). "TIPE2 significantly reduced the tumor volume compared with vector group during the progression of pancreatic cancer." (PMID 34249724, 2021). "And the results showed that the tumor sizes of TIPE2 group were significantly smaller than vector group during the development of pancreatic cancer." (PMID 34249724, 2021). "To further investigate the clinical significance of TIPE2 expression in pancreatic cancer, we analyzed the relationship between TIPE2 expression and clinico-pathological features." (PMID 34249724, 2021). "To further explore the mechanism of TIPE2 in the metastasis of pancreatic cancer cells, we detected the expression of EMT markers, MMPs and N-cadherin." (PMID 34249724, 2021). "The results showed that TIPE2 suppressed both the migration and invasion abilities of pancreatic cancer cells." (PMID 34249724, 2021). "To evaluate the role of TIPE2 in pancreatic cancer, we overexpressed TIPE2 in pancreatic cancer cell lines with lentivirus, including human cell lines AsPC-1 and BxPC-3, and mouse cell line Panc02, which have low level of TIPE2 expression." (PMID 34249724, 2021). "To investigate the mechanism of the immune antitumor effect of TIPE2 in pancreatic cancer, we analyzed the tumor-infiltrating lymphocytes via flow cytometry." (PMID 34249724, 2021). "To explore the immune function of TIPE2 in the development of pancreatic cancer in vivo, we injected Panc02/vector and Panc02/TIPE2 cells into C57BL/6 mice to establish the subcutaneous tumor model." (PMID 34249724, 2021). "And we also confirmed TIPE2 was overexpressed in the pancreatic tumor tissues isolated from mice through immunohistochemical staining." (PMID 34249724, 2021). "The expression of TIPE2 was analyzed in pancreatic carcinoma and paracancerous tissues using immunohistochemistry." (PMID 34249724, 2021). "TIPE2 expression also significantly increased cell apoptosis of the pancreatic cancer cells." (PMID 34249724, 2021).
pancreatic cancer (continued). "Furthermore, TIPE2 indeed reduced the expression of Ki-67 and N-cadherin, increased the expression of Bax, and suppressed the tumor growth of pancreatic cancer in mouse xenograft tumor models." (PMID 34249724, 2021). "Indeed, TIPE2 inhibited the growth of pancreatic cancer in mice subcutaneous tumor model and the expression of TGFβ1 in tumor cells was suppressed." (PMID 34249724, 2021). "In general, we described the multiple regulatory mechanisms of TIPE2 in pancreatic tumorigenesis and tumor microenvironment, which suggested TIPE2 may act as a potential therapeutic target in pancreatic cancer." (PMID 34249724, 2021). "Furthermore, we tried to peek into the mechanism of TIPE2 that mediates the function of pancreatic cancer cells." (PMID 34249724, 2021). "Therefore, TIPE2 possibly suppressed the growth of pancreatic cancer through inhibiting TGFβ1 expression." (PMID 34249724, 2021). "In summary, we described the multiple regulatory mechanisms of TIPE2 in pancreatic tumorigenesis and tumor microenvironment, based on the result obtained it is suggested that TIPE2 may serve as a potential therapeutic target in pancreatic cancer." (PMID 34249724, 2021). "Moreover, the results obtained from real time PCR and western blot revealed that TIPE2 was also involved in inhibiting MMPs and N-Cadherin expression while increasing Bax expression in pancreatic cancer cells." (PMID 34249724, 2021). "TIPE2 markedly inhibited cell proliferation of pancreatic cancer cells using CCK-8 assay." (PMID 34249724, 2021). "Relationship between TIPE2 expression and clinico-pathological features in pancreatic cancer." (PMID 34249724, 2021). "Mechanistic studies exhibited that TIPE2 might suppress pancreatic cancer development through inhibiting PI3K/AKT and Raf/MEK/ERK signaling pathways triggered by TGFβ1." (PMID 34249724, 2021). "Overexpression of TIPE2 in pancreatic cancer cells could inhibit cell proliferation, and increase cell apoptosis." (PMID 34249724, 2021). "However, the role of TIPE2 is still not fully understood in pancreatic cancer." (PMID 34249724, 2021). "We also found that TIPE2 could upregulate the expression of pro-apoptotic protein Bax, while Bax was involved in the regulation of apoptosis and could influence the prognosis of pancreatic cancer patients." (PMID 34249724, 2021). "Therefore, TIPE2 might exert an anti-tumor effect by activation T cells through DCs in a TGFβ1 dependent manner in pancreatic cancer." (PMID 34249724, 2021). "Furthermore, we found that TIPE2 could promote T cell and DC activation to inhibit the development of pancreatic cancer." (PMID 34249724, 2021). "Therefore, TIPE2 might suppress the metastasis of pancreatic cancer cells through inhibiting the EMT process." (PMID 34249724, 2021). "Research showed that TIPE2 can regulate tumorigenesis not just directly from the interior of tumor cells, but also indirectly through immune cells in pancreatic cancer." (PMID 36801818, 2023). "We demonstrated that TIPE2 could reduce the phosphorylation of ERK and AKT in pancreatic cancer cells." (PMID 34249724, 2021). "Similarly, TIPE2 overexpression could decrease the protein level of TGFβ1 and phosphorylation of TGFBR1 in pancreatic cancer." (PMID 34249724, 2021). "Furthermore, TIPE2 could not only inhibit the secretion of TGFβ1, but also decrease the phosphorylation of TGFBR1 in pancreatic cancer cells." (PMID 34249724, 2021). "However, whether TIPE2 is involved in pancreatic cancer is still not fully understood." (PMID 34249724, 2021).
papillary thyroid cancer (2 papers, 2018 to 2025). "TIPE2 has been known as a cancer suppressor in different malignancies such as kidney, colon, and papillary thyroid cancers." (PMID 40060230, 2025).
psoriasis (2 papers, 2019 to 2021). An autoimmune condition characterized by red, well-delineated plaques with silvery scales that are usually on the extensor surfaces and scalp. "Instead, they migrate to the inflamed eye in a similar manner to TIPE2-deficient T cells and thus exacerbate the development of EAU in TIPE2-deficient mice but reduce the severity of psoriasis in these animals." (PMID 34795583, 2021). "In contrast to the phenotype difference displayed in IMQ-induced psoriasis model, TIPE2-deficient mice exhibited more severe retinal edema and structural distortion in the EAU model." (PMID 31616442, 2019). "Our study revealed that, while TIPE2-deficiency alleviates psoriasis, it exacerbates the development of EAU." (PMID 31616442, 2019). "This in turn led to the decreased IL-17A production in the skin and consequently reduced the severity of psoriasis in TIPE2-deficient mice." (PMID 31616442, 2019). "In order to directly test the T cell–specific function of TIPE2 in psoriasis, we studied the IMQ-induced psoriasis in Rag1−/− mice that had received WT or TIPE2-deficient T cells." (PMID 31616442, 2019). "This would explain why TIPE2-deficient mice develop less severe IMQ-induced psoriasis." (PMID 31616442, 2019). "Since TIPE2 functions as a negative regulator of adaptive immune response, we speculate that TIPE2-deficient mice will be more susceptible to developing psoriasis and EAU." (PMID 31616442, 2019). "Although TIPE2-deficient T cells produced more IL-17A, TIPE2-deficient mice produced much less IL-17A in the skin and displayed reduced severity of IMQ-induced psoriasis." (PMID 31616442, 2019). "To determine how TIPE2 affects T cell migration during the development of psoriasis, we examined the expression of multiple chemokine receptors on the surface of CD3+ T cells from the ILN and blood of IMQ-treated WT and TIPE2-deficient mice." (PMID 31616442, 2019). "Because we have shown that TIPE2 suppresses IL-17A production by T cells during the development of IMQ-induced psoriasis, the percentage and absolute number of CD3+IL-17A+ T cells was significantly increased in the blood and ILN as expected." (PMID 31616442, 2019). "In the current study, we sought to determine the role of TIPE2 during the development of IMQ-induced psoriasis and Experimental Autoimmune Uveitis (EAU) in mice." (PMID 31616442, 2019). "Next we focused on the roles of TIPE2 in regulating T cell migration during the development of IMQ-induced psoriasis." (PMID 31616442, 2019). "Our study revealed that, although TIPE2 exacerbates the development of psoriasis through promoting the directional migration of T cells to the site of inflammation, it alleviates EAU through the suppression of IL-17A production by T cells." (PMID 31616442, 2019). "In the current study, we sought to determine the role of TIPE2 during the development of IMQ-induced psoriasis and EAU in mice." (PMID 31616442, 2019). "In the current study we further confirmed that TIPE2 may promote T cell migration via the same mechanism in the psoriasis model." (PMID 31616442, 2019). "However, our current study showed that, while TIPE2-deficient mice develop more severe EAU, they unexpectedly develop less severe IMQ-induced psoriasis." (PMID 31616442, 2019). "Taken together, these results indicate that, although TIPE2-deficient T cells produced more IL-17A in both disease models, they are defective in migration to the skin in IMQ-induced psoriasis model but not to the eye in EAU model." (PMID 31616442, 2019).
squamous cell carcinoma (2 papers, 2016 to 2019). A carcinoma arising from squamous epithelial cells. "More importantly, although TIPE2 was highly expressed in squamous cell carcinoma and adenocarcinoma, we found that TIPE2 expression decreased markedly in tumor tissues with lymph node metastasis." (PMID 27556698, 2016). "In addition, upon comparing the differential expression of TIPE2 with respect to disease pathology, it was observed that TIPE2 exerted significant upregulation in adenocarcinoma and squamous cell carcinoma." (PMID 31817720, 2019). "Results showed that comparing to adjacent tissues, TIPE2 protein was highly expressed in all histological subtypes of NSCLCs arrayed, including squamous carcinoma, adenocarcinoma, adeno-squamous carcinoma, bronchoalveolar carcinoma and large cell lung carcinoma." (PMID 27556698, 2016).
Stroke (2 papers, 2021 to 2023). Sudden impairment of blood flow to a part of the brain due to occlusion or rupture of an artery to the brain. "In the TIPE2-/- mice stroke model, it was discovered that TIPE2 deficiency increased the amount of neutrophils and macrophages, and elevated the scope of cerebral ischemic injury." (PMID 36983674, 2023).